CAV1 (caveolin 1)
Diseases named in the same sentence as CAV1 in open-access papers (continued):
Sharing a sentence is not in itself a finding about the gene and the disease.
rheumatoid arthritis (6 papers, 2015 to 2025). A chronic, systemic autoimmune disorder characterized by inflammation in the synovial membranes and articular surfaces. "Moreover, miR-192-5p was reported to inhibit proliferation and induce the apoptosis of human rheumatoid arthritis fibroblast-like synoviocytes (FLS) by targeting caveolin 1, suggesting a pro-inflammatory function and destructive role of miR-192-5p in RA." (PMID 33708127, 2021). "The outer membrane vesicles (OMVs) of P. goldsteinii translocate to arthritic joints, where they activate the Cav-1–Nrf2 axis to suppress neutrophil extracellular trap (NET) formation, thereby alleviating rheumatoid arthritis (RA) severity." (PMID 41019532, 2025). "CAV1, a gene belonging to the cytokine-mediated signaling pathway, was found to be one of the genes characterizing MTX non-responders in patients with rheumatoid arthritis (RA)." (PMID 25915206, 2015).
schizophrenia (6 papers, 2017 to 2022). A major psychotic disorder characterized by abnormalities in the perception or expression of reality. "A relationship between CAV1 and Huntington disease was reported, and CAV1 was found to be a risk gene for schizophrenia." (PMID 32082483, 2020). "Although no report exists about caveolin contribution to major depression the Cav-1 is linked to schizophrenia in both human polymorphism study and in Cav-1 knockout animals." (PMID 29163047, 2017). "Considering that schizophrenia is a neurodevelopmental disorder and that the expression of mHtt disturbs neuronal migration in the developing cerebral cortex, it implies that caveolin-1 may have a role in neural development." (PMID 30267686, 2018).
acne (5 papers, 2019 to 2025). An inflammatory process of the sebaceous glands which is characterized by comedones, nodules, papules and/or pustules on the skin. "We have argued that CAV1 must be also strongly involved in the pathophysiology of acne and serve as a target in the treatment of this cutaneous condition." (PMID 39552138, 2025). "This pathophysiology of acne was substantially revised in the recent past after the discovery of the role of dermal adipocytes and caveolin‐1 (CAV1) in the development of inflammatory and hyperproliferative conditions in the vicinity of PSUs." (PMID 39552138, 2025). "Similarly, applying salicylic acid significantly stimulated CAV1 expression, and an increase in the level of this protein strongly correlated with amelioration of acne lesions." (PMID 41516288, 2025). "For example, Cav-1 has been suggested as a target for treating acne." (PMID 39791703, 2024). "Low levels of CAV1 are also typical in acne vulgaris but not in hidradenitis suppurativa, in which it is significantly overexpressed." (PMID 41516288, 2025). "Since CAV1 is not just a pathophysiological factor but also a target in various inflammatory skin conditions, any methods that effectively modulate its expression in lesional/perilesional areas should be effective in the treatment of acne." (PMID 39552138, 2025).
acute kidney injury (5 papers, 2013 to 2026). Sudden and sustained deterioration of the kidney function characterized by decreased glomerular filtration rate, increased serum creatinine or oliguria. "Notably, CAV1 is predominantly expressed in glomeruli and renal tubular cells and is implicated in the initiation and progression of various renal disorders, including acute kidney injury (AKI), diabetic nephropathy, and IgA nephropathy." (PMID 39887553, 2025). "Namely, Caveolin-1 may have a possible role in the pathophysiology of acute kidney injury by regulating cellular metabolism and activities regarding cellular life." (PMID 39062115, 2024). "Cav-1 is involved in the pathophysiology of acute kidney injury (AKI)." (PMID 34955837, 2021).
cerebral infarct (5 papers, 2012 to 2025). "It has been reported that caveolin-1 deficient mice showed a more severe cerebral infarction than did wild-type mice and that MCAo-reperfusion led to an increase in iNOS expression and NO production as well as a decrease in caveolin-1 protein at the core and penumbra of the ischemic brain." (PMID 24961257, 2012). "In vivo animal experiment results also indicated apigenin affected the Caveolin-1/VEGF pathway to attenuate cerebral infarction injury in rats of MCAO/R." (PMID 30622670, 2018). "Results of our previous study also indicated that upregulating the Caveolin-1/VEGF decreased cerebral infarct volume, promoted neurological recovery, and facilitated angiogenesis and neurogenesis." (PMID 30622670, 2018). "Caveolin-1 inhibitor intervention increased the volume of cerebral infarction (P < 0.05)." (PMID 30622670, 2018). "Interestingly, cav-1 seems to play a role in tPA-induced MMP-9 activation in the ischemic brain, which exaggerates brain infarction and increases the risk of symptomatic cerebral hemorrhage." (PMID 30572925, 2018). "We have demonstrated that Caveolin-1 decreased cerebral infarct volume, facilitated angiogenesis and neurogenesis, and promoted neurological recovery by upregulating the Caveolin-1/VEGF signaling pathway in a rat model of middle cerebral artery occlusion (MCAO) in our previous study." (PMID 30622670, 2018). "Previous studies reported that Caveolin-1 gene ablation in mice could induce increased cerebral infarction volume and cell death, decreased VEGF expression, and impaired angiogenesis." (PMID 30622670, 2018). "The phosphorylated Cav-1 binds to the BECN1/VPS34 complex and translocates into mitochondria, where it further induces autophagy, thereby alleviating cerebral infarct damage in a mouse cerebral ischemia model." (PMID 41030451, 2025). "Cav-1 OE decreases brain edema in a rat MCAO model, and cav-1 KO increases brain infarction volume." (PMID 30572925, 2018).
edema (5 papers, 2015 to 2024). An abnormal accumulation of fluid beneath the skin, or in one or more cavities of the body. "The severity of brain edema due to various types of brain injury is closely linked to CAV-1 expression." (PMID 36253854, 2022). "Cav-1 is an integral protein for caveolae formation, with upregulation associated with enhanced albumin extravasation and the development of vasogenic cerebral edema." (PMID 31333402, 2019). "Our investigation of the role of Cav-1 in A. cantonensis-induced eosinophilic meningoencephalitis, which leads to brain damage, cerebral hemorrhage, and cerebral edema, revealed an increase in Cav-1 levels in the brains of infected mice." (PMID 38922036, 2024). "In the initial state of acute lung injury, Cav-1 contributes to polymorphonuclear neutrophil-mediated inflammation, vascular injury and non-cardiogenic pulmonary edema." (PMID 25756273, 2015).
esophageal squamous cell carcinoma (5 papers, 2011 to 2024). Esophageal squamous cell carcinoma (ESCC) is a type of esophageal carcinoma (EC) that can affect any part of the esophagus, but is usually located in the upper or middle third. "Recently, miR-138 was reported to be down-regulated in esophageal squamous cell carcinoma (ESCC) and the markers of lipid rafts FLOT1, FLOT2 and caveolin-1 were identified as its targets, and NF-kappaB was activated." (PMID 24204780, 2013). "CAV1 hypermethylation showed highly discriminative ROC curve profiles, clearly distinguishing esophageal adenocarcinomas (EAC) and esophageal squamous cell carcinomas (ESCC) from normal esophagus (NE) (EAC vs. NE, AUROC = 0.839 and p < 0.0001; ESCC vs. NE, AUROC = 0.920 and p < 0.0001)." (PMID 24885118, 2014).
heart failure (5 papers, 2020 to 2025). Inability of the heart to pump blood at an adequate rate to meet tissue metabolic requirements. "We previously demonstrated that CSD (aa 82–101 of caveolin-1) has a wide range of beneficial effects in two distinct mouse heart failure models (TAC and AngII-induced disease) and in bleomycin-induced lung and skin fibrosis." (PMID 35213624, 2022). "Cav-1 is beneficial for limiting the development of heart failure." (PMID 40041164, 2025). "Interestingly, several genes including NKX2-5, ATP2A2 and CAV1 involved in these pathways were also found in toxicity pathways such as failure of heart, congenital heart disease, congestive heart failure, dilation of heart chamber and dilation of left ventricle." (PMID 31948008, 2020).
inflammatory breast carcinoma (5 papers, 2008 to 2020). An advanced, invasive breast adenocarcinoma characterized by the presence of distinct changes in the overlying skin. "Furthermore, high caveolin-1 levels mediate inflammatory breast cancer (IBC) cell invasion by activating Akt1, which in turn causes RhoC GTPase phosphorylation." (PMID 31148948, 2019).
Lipedema (5 papers, 2021 to 2026). Disorder of adipose tissue characterized by symmetric and bilateral enlargement of the lower extremities due to abnormal deposition of subcutaneous fat often in obese women. "Alterations in the function of structural protein, such as CAV1 dysfunction, and genetic factors, such as mutations in AKR1C1, further point toward a hormone-sensitive and possibly inherited component in lipedema." (PMID 41575573, 2026). "Complementing this, it has been proposed that lipedema is an estrogen-dependent adipose disorder triggered by CAV1 dysfunction." (PMID 41575573, 2026). "An illustrative example is lipedema, which has been proposed as an estrogen-sensitive adipose disorder possibly initiated by caveolin-1 (CAV1) dysfunction." (PMID 41303617, 2025). "An intriguing hypothesis for lipedema pathogenesis involves improper ECM remodeling, whereby uncoupling of the MMP-14-caveolin 1 (CAV1) axis in adipocytes may cause aberrant matrix processing, resulting in hypertrophic SAT expansion." (PMID 35743063, 2022). "An ECM/lymphatic-related signaling mechanism hypothesized for the pathophysiology of lipedema is the matrix metallopeptidase 14 (MMP14)–caveolin-1 (CAV-1) axis, wherein MMP14 and CAV-1 are mutually regulated through a feedback mechanism." (PMID 36551837, 2022). "Recently, lipedema has been presented as a potential estrogen-dependent adipose tissue disorder that could be triggered by caveolin-1 (CAV1) dysfunction." (PMID 33800991, 2021). "Thus, impairment of estrogen signaling may also be a culprit in the lymphatic dysfunction in lipedema, as has been hypothesized with the MMP14–caveolin-1 (CAV-1) axis mechanism." (PMID 36551837, 2022).
myocardial ischemia (5 papers, 2013 to 2022). A disorder of cardiac function caused by insufficient blood flow to the muscle tissue of the heart. "Using a rat model of LAD ligation-induced myocardial ischemia, we demonstrated the effects of GTP treatment for 2 weeks on the expression of LR and Cav-1 and -3 in the myocardium." (PMID 24251870, 2013).
osteoporosis (5 papers, 2015 to 2025). A condition of reduced bone mass, with decreased cortical thickness and a decrease in the number and size of the trabeculae of cancellous bone (but normal chemical composition), resulting in increased fracture incidence. "In order to identify the role of Cav-1 in the occurrence and development of osteoporosis, sham-operation or ovariectomy was performed and bone micro architecture was analysized by micro-CT." (PMID 37868048, 2023). "In vivo, kirenol (2–10 mg/kg) reduced ovariectomy (OVX)-induced osteoporosis, as demonstrated by the decrease in the osteoclast number and the downregulation of Cav-1 and NFATc1 expression." (PMID 35163999, 2022). "The results of the current study also showed that CTNNB1 and CAV1 were significantly downregulated in the osteoporosis samples, while SHC1, AKT1 and FLNA were upregulated." (PMID 25815782, 2015). "In this case, we expect Cav-1/EGFR signaling pathway may be another potential anti-osteoporosis therapeutic target." (PMID 37868048, 2023). "We uncovered another interpretation for daidzein ameliorating osteoporosis by inhibiting Cav-1." (PMID 37868048, 2023). "We hypothesized that Cav-1 mediating senescence of endothelial cells could be an interpretation for impaired H-type vessel formation and the resultant osteoporosis." (PMID 37868048, 2023). "Additionally, kirenol protects against OVX-induced osteoporosis by suppressing osteoclastogenesis and the Cav-1/NFATc1 signalling pathways both in vitro and in vivo." (PMID 35163999, 2022). "Previous studies have shown that Caveolin-1 (Cav-1) is a functional regulator of osteoclast differentiation, and silencing Cav-1 can inhibit osteoclast formation and prevent OVX-induced osteoporosis." (PMID 41208864, 2025). "According to the colocalization staining of EMCN and Cav-1, we observed daidzein rescued OVX-induced osteoporosis by inhibiting Cav-1 and promoting blood vessels formation." (PMID 37868048, 2023). "Silencing caveolin-1 results in inhibition of osteoclast formation and protection against ovariectomy (OVX)-induced osteoporosis." (PMID 37868048, 2023). "Recent studies demonstrated that inhibiting caveolin-1 leads to osteoclastogenesis suppression and protection against OVX-induced osteoporosis." (PMID 37868048, 2023).
pancreatic ductal adenocarcinoma (5 papers, 2002 to 2021). An infiltrating adenocarcinoma that arises from the epithelial cells of the pancreas. "Caveolin-1 (Cav-1) plays a key role in various neoplastic diseases and is upregulated in different cancers, including pancreatic ductal adenocarcinoma (PDAC)." (PMID 34590611, 2021). "Additionally, caveolin-1 overexpression is related to tumour size and histopathological stage in both pancreatic ductal carcinoma and oesphageal squamous cell carcinoma." (PMID 14612902, 2003).
Right ventricular hypertrophy (5 papers, 2012 to 2024). In this case the right ventricle is more muscular than normal, causing a characteristic boot-shaped (coeur-en-sabot) appearance as seen on anterior- posterior chest x-rays. "CAV1+/−/Cavin-1+/− mice also showed improved right ventricular hypertrophy and pulmonary vascular remodeling, as observed in CAV1+/− mice." (PMID 38182755, 2024). "Similarly, another study found that Cav-1 knock-out mice displayed dilated left ventricles and right ventricular hypertrophy." (PMID 24454806, 2014).
steatosis (5 papers, 2017 to 2022). Increased lipid within the cytoplasm of cells. "The association of CAV1 gene expression loss with increased lipid accumulation suggested its potentially protective role against FFA-induced hepatocyte steatosis." (PMID 28570612, 2017). "Notably, H&E staining and Oil Red O staining revealed severe steatosis with various sizes of lipid deposition in the livers of CAV1-deficient mice fed an HFD for 4 weeks compared to the livers of WT littermates." (PMID 28570612, 2017). "Using in vitro CAV1 loss- and gain-of-function studies, the ability of CAV1 to sufficiently protect against FFA-induced hepatocyte steatosis was revealed." (PMID 28570612, 2017). "By combining the CRISPR-Cas9 system with the adenovirus recombination technique, we developed stable CAV1-knockdown (CAV1-KD) AML12 hepatocyte cell lines to determine the influence of inherent CAV1 depletion on hepatocyte steatosis." (PMID 28570612, 2017). "Here, our results showed that both FASN and ACC protein expression was upregulated upon CAV1 knockdown but downregulated upon CAV1 overexpression in FFA-induced hepatocyte steatosis." (PMID 28570612, 2017). "Our results indicated that depletion of CAV1 significantly aggravated FFA-induced steatosis in L02 cells as determined by Oil Red O staining." (PMID 28570612, 2017). "Collectively, these gain-of-function results confirmed the ability of CAV1 to sufficiently protect against FFA-induced hepatocyte steatosis." (PMID 28570612, 2017). "Similarly, mice with caveolin-1 knockdown had augmented steatosis, increased plasma cholesterol, and elevated liver injury enzymes, whereas overexpression of the gene resulted in significantly attenuated lipid accumulation in hepatocytes." (PMID 36233107, 2022). "Early studies found that caveolin-1 levels were increased in mice fed a steatosis-inducing high-fat diet for 14 weeks, indicating that caveolins may be implicated in the pathogenesis of NAFLD." (PMID 36233107, 2022). "Differential observations suggest that the role of caveolin 1 in hepatic lipid accumulation may differ depending on how the steatosis is induced, e.g., via high fat diet or fasting." (PMID 29936596, 2018). "Furthermore, caveolin 1 knockout augmented steatosis both in vitro and in vivo by enhancing the expression of genes involved in DNL, contradicting earlier studies, and suggesting a protective effect of caveolin 1 in NAFLD." (PMID 29936596, 2018). "However, one study showed that the expression of CAV1 in mice is required for efficient hepatic lipid storage during fasting, liver regeneration, and diet-induced steatosis in three CAV1-/- mouse strains." (PMID 28570612, 2017). "Thus, it can be speculated that CAV1 plays an important role in protecting against steatosis-induced hepatic impairment." (PMID 28570612, 2017). "Plin5−/− livers had an increased expression of CAV1 under NC and HFD in comparison with WT, supporting our results for reduced steatosis and liver damage in those mice." (PMID 32481590, 2020). "CAV1 expression was repressed in L02 and AML12 cells cultured with free fatty acids to trigger steatosis in vitro." (PMID 32029710, 2020). "Caveolin 1 was increased in the liver of mice with NAFLD, and located mainly in the centrilobular zone 3, where the steatosis was most severe." (PMID 29936596, 2018). "CAV1 knockdown led to the aggravation of steatosis that was induced by FFA in both L02 cells and AML12 cells, while CAV1 overexpression markedly attenuated lipid accumulation in the cells." (PMID 28570612, 2017).
Anxiety (4 papers, 2014 to 2025). Intense feelings of nervousness, tension, or panic often arise in response to interpersonal stresses. "In contrast, models with Cav1.2cKO in both excitatory and inhibitory neurons exhibit normal anxiety-like behaviour." (PMID 40565009, 2025). "Next, we subjected Cav1.2-Nex mice to a series of behavioral tests to assess locomotion, anxiety-related behavior, cognitive performance, and stress-coping strategies." (PMID 39370418, 2024). "In summary, Cav1.3AG mutant mice displayed a gene-dose–dependent behavioral phenotype comprising enhanced locomotor activity upon exposure to a novel environment, aberrant grooming/rearing, enhanced anxiety-like behavior, and decreased sociability." (PMID 37698939, 2023). "Moreover, Cav-1 KO mice have previously been shown to exhibit enhanced anxiety and impaired spatial memory, demonstrating an important role for Cav-1 in normal neurological phenotype." (PMID 24593993, 2014).